RN7SKP154 (RN7SK pseudogene 154)
Gene: Miscellaneous RNA gene on chromosome 2 (133,391,109 to 133,391,398, reverse strand). Ensembl gene ENSG00000222068.
Homologues: Orthologues: chimpanzee 7SK (98% identical), mouse Gm55575 (55% identical), guinea pig 7SK (55% identical). Paralogues in human: RN7SKP180 (76% identical), RN7SKP176 (75% identical), 7SK (74% identical), RN7SKP9 (74% identical), RN7SKP193 (73% identical), RN7SKP37 (73% identical), RN7SKP1 (73% identical), RN7SKP103 (72% identical), RN7SKP171 (72% identical), RN7SKP124 (72% identical), RN7SKP185 (72% identical), RN7SKP217 (72% identical), and 283 more.